RN7SL718P (RNA, 7SL, cytoplasmic 718, pseudogene)
Gene: Miscellaneous RNA gene on chromosome 19 (41,190,927 to 41,191,229, reverse strand). Ensembl gene ENSG00000264423.
Homologues: Paralogues in human: RN7SL602P (86% identical), RN7SL440P (82% identical), Metazoa_SRP (82% identical), Metazoa_SRP (81% identical), RN7SL524P (81% identical), Metazoa_SRP (80% identical), Metazoa_SRP (78% identical), RN7SL121P (77% identical), Metazoa_SRP (77% identical), Metazoa_SRP (76% identical), RN7SL387P (76% identical), RN7SL525P (76% identical), and 711 more.